MST1 (macrophage stimulating 1)
Diseases named in the same sentence as MST1 in open-access papers (continued):
Sharing a sentence is not in itself a finding about the gene and the disease.
prostate carcinoma (15 papers, 2010 to 2024). A carcinoma that arises from epithelial cells of the prostate gland. "The mTOR signaling pathway also regulates MST1 phosphorylation at T120 and that this phosphorylation results in loss of MST1 function in prostate cancer cells." (PMID 27042197, 2016). "Additionally, MST1 and MST4 have been implicated in prostate cancer, whereby MST1 protein levels declined with disease progression and MST4 expression has been correlated with tumourigenicity of human prostate cancer cell lines." (PMID 20730082, 2010). "Of note, MST1 degradation promoted through its physical interaction with HSP70 mediates cisplatin resistance in prostate cancer cells." (PMID 35954292, 2022). "Concordance was now observed only for three phenotypes (inflammatory bowel disease, prostate cancer, obesity-related phenotypes) and a total of 3 genes (MST1, MSMB and SH2B1, respectively)." (PMID 21072174, 2010). "In contrast, overexpression of MST1 augments cisplatin-induced apoptosis in prostate cancer cells." (PMID 33467099, 2021). "Moreover, in prostate cancer, MST1 was found to interact with heat shock protein 70 (Hsp70), and the functional consequences of this interaction are the degradation of MST1 and cisplatin resistance." (PMID 33467099, 2021). "An in vitro study showed that MST1 suppressed prostate cancer growth." (PMID 31748686, 2019). "Finally, data demonstrate that the phosphorylation of MST1/2 can be induced by the mTOR signaling pathway and restrict MST1/2 function to inhibit cell growth in prostate cancer cells." (PMID 26909043, 2016). "Taken together, these data support the hypothesis that targeting TYK2 and/or MST1 with specific inhibitors could be a useful approach in the blockage of prostate cancer progression in ETV1- positive PCa." (PMID 26097883, 2015). "In colon cancer, GRPR enhances invasion through the RhoA/ROCK pathway, while in prostate cancer, GRPR overexpression promotes a malignant phenotype via activation of AKT1, PKCε, TYK2, and MST1 pathways." (PMID 39768218, 2024). "Cinar reported that MST1 is cleaved by caspase, and mature MST1 and cleavage products are inhibited by AKT in human prostate cancer cells." (PMID 38274792, 2023). "MST1 has also been reported to be suppressed by miR-18a or downregulated via epigenetic silencing mediated by c-Myc and EZH2 in prostate cancer." (PMID 35954292, 2022). "It was shown that knockdown of MST1 increased YAP1 nuclear localization and YAP1-AR interactions in prostate cancer cells, which correlated with augmented cell growth independent of androgen exposure, whereas expression of ectopic MST1 had the opposite effect." (PMID 35954292, 2022). "It has also been shown that MST1 may directly interact with and inhibit the AKT1 serine/threonine kinase in human prostate cancer cells." (PMID 35954292, 2022). "Moreover, MST1 is the key kinase component of the Hippo-YAP pathway, which restricts prostate cancer progression by interacting with multiple molecular pathways." (PMID 31748686, 2019). "To determine the mechanism by which STK4/MST1 signaling controls EPHA3 expression, we first assessed the abundance of the Ephrin A (EphA) and Ephrin B (EphB) receptor subtypes and their respective ligands in the well-characterized human prostate cancer cell lines LNCaP, C4-2, 22Rv1, and PC3." (PMID 35264657, 2022). "We noted that many Hippo pathway SNPs (one in MST1, three in STK3, two in LATS2, one in MOB1B, and six in WWTR1; total 13 out of 75) genotyped in our prostate cancer patient cohort were not in Hardy-Weinberg equilibrium (HWE)." (PMID 25707771, 2015).
cardiomyopathy (14 papers, 2015 to 2025). A disease of the heart muscle or myocardium proper. "There was a high degree consistency between current study on DOX-induced cardiomyopathy and Mst1-TG model 21 in changes of Hippo pathway activation, mitochondrial damage and onset of cardiomyopathy." (PMID 36632235, 2023). "We found that in different cardiomyopathy models (Mst1-TG mice, β2-AR-TG mice, the I/R model and mice treated with isoproterenol), the density of macrophages within myocardial tissue was different between each other." (PMID 35004876, 2021). "First, Gal-3 levels in plasma were different between two mouse models of cardiomyopathy (i.e., Mst1-TG mice and β2-AR TG mice)." (PMID 35004876, 2021). "Mst1 signal pathways are involved in many cardiovascular diseases, including atherosclerosis, myocardial ischemic injury and cardiomyopathy." (PMID 33553168, 2020). "Although we started the interventions at 7 weeks of age, there is evidence that Mst1 transgenic mice have signs of cardiomyopathy as early as 15 days of age13." (PMID 33087738, 2020). "Consistent with the cardiomyopathy phenotype, Mst1 mice displayed evidence of lung congestion as reflected by an increase in lung weight and lung weight indexed to body weight." (PMID 30837882, 2019). "Although Mst1 exerts a pivotal regulatory function during the progression of β1-AR-induced cardiomyopathy, the mechanism of action between Mst1 and β1-AR-activated signaling pathways remains unclear." (PMID 41372115, 2025). "Therefore, this study aimed at exploring for the first time the role of MST1 in the development of DOX-induced cardiomyopathy." (PMID 37566283, 2023). "In summary, MST1 contributes to DOX-induced cardiomyopathy through SIRT3 downregulation." (PMID 37566283, 2023). "Minipumps were implanted subcutaneously in wild‐type mice (n = 20) and mice with cardiomyopathy secondary to cardiac specific overexpression of mammalian sterile 20‐like kinase 1 (MST‐1; n = 18) to administer N‐acetylcysteine (40 mg/kg per day) or saline for a period of 8 weeks." (PMID 27081162, 2016). "Moreover, a mouse strain with cardiac-specific overexpression of Mammalian Sterile 20-Like Kinase 1 (Mst1/Stk4) develops cardiomyopathy and has reduced plasmalogen levels, which was hypothesized to play a causative role for the cardiac defect." (PMID 36768204, 2023). "Interestingly, ISO treatment to Mst1-TG cardiomyopathy mice increased circulating Gal-3." (PMID 29844319, 2018). "Studies have shown that Mst1 reduces apoptosis in non-cardiomyocytes (such as fibroblasts, macrophages, neutrophils) and necrosis in cardiomyocytes, thereby ameliorating cardiomyopathy." (PMID 41372115, 2025). "Moreover, we show for the first time that inhibiting MST1 with pharmacological agents, such as XMU-MP-1, represents a novel translational approach to prevent the occurrence of DOX-induced cardiomyopathy." (PMID 37566283, 2023).
gastric cancer (14 papers, 2016 to 2025). A primary or metastatic malignant neoplasm involving the stomach. "In the context of the Hippo pathway in gastric cancer, Striatin 3 facilitates MST1/2 dephosphorylation through protein phosphatase 2A (PP2A), activating YAP and driving gastric cancer progression." (PMID 40066231, 2025). "Treatment of gastric cancer cells and human xenografts in mice with ursolic acid activated the kinases MST1, MST2, and LATS1 and inhibited YAP1, leading to decreased proliferation and metastases." (PMID 39768557, 2024). "We previously identified STRN3-containing PP2A phosphatase as a negative regulator of MST1/2 kinases (i.e., Hippo) in gastric cancer (GC), opening the possibility of selectively targeting the PP2Aa–STRN3–MST1/2 axis to recover Hippo signaling against cancer." (PMID 38657866, 2024). "Although up-regulation of MST1 has been observed in some cancers, MST1 has been reported to be down-regulated in gastric cancer and exert a tumour suppressive function." (PMID 29079854, 2017). "In this regard, we recently discovered an upregulation of STRN3 in gastric cancer (GC) cells, with STRN3 recruiting MST1/2 to the PP2A core enzyme to dephosphorylate MST1/2, a process that turns off the tumor-suppressive activity of Hippo signaling." (PMID 35290241, 2022). "Similar to the gene expression profiling results, the protein levels of RASSF1, MST1, MST2, LATS1, and p-YAP were increased, whereas those of CTGF were decreased by UA in gastric cancer cells." (PMID 31547587, 2019). "In agreement with the gene expression profiling study, we found that UA increased the expression of the Hippo signaling pathway proteins Mst1, Mst2, p-Mob1, and LATS1 in gastric cancer cells." (PMID 31547587, 2019). "For example, decreased expressions of Mst1/2 and LATS are found in gastric cancer, and overexpressed YAP proteins are strongly related to a poor prognosis of patient survival." (PMID 27230238, 2016). "MST1 is the upstream-negative regulatory molecule of p38-MAPK, which may have an important regulatory role in gastric cancer and other malignant tumors and certain organogenesis; however, research on the pathogenesis of endometriosis is rarely reported." (PMID 36263059, 2022). "In gastric cancers, expression of the Hippo pathway transcription factors YAP1 and TEAD was up-regulated in parallel with CDX2, while the negative regulators of the pathway, serine/threonine kinases MST1 and LATS1, were down-regulated, compared with normal gastric epithelia." (PMID 39768557, 2024). "Similarly, MST1R had interactions with AKT, AKT1, and MST1, while LTR interacted with IRS1, CBL, PIK3C and SHC1, none of which have been found to be associated with gastric cancer before." (PMID 37287033, 2023). "We then assessed the interaction of AGK and Hippo‐YAP1 pathway in gastric cancer cells and found that AGK overexpression was able to up‐regulate level of YAP1 and CTGF proteins, but lead to a down‐regulation of the level of LATS1/2 and p‐YAP without changing in MST1/2 levels." (PMID 32827244, 2020).
lymphopenia (14 papers, 2012 to 2022). Reduction in the number of lymphocytes. "In humans, nonsense mutations that cause a functional deficiency of the protein MST1 provoke an immunodeficiency syndrome characterized by severe lymphopenia, transient neutropenia, and recurrent bacterial and viral infections." (PMID 36618429, 2022). "STK4/MST1-deficient mice were shown to accumulate mature thymocytes in the thymus, which was associated with peripheral T cell lymphopenia." (PMID 34867982, 2021). "Patients with STK4/MST1 deficiency have a profound CD4 lymphopenia with very low circulating naive CD4 and CD8 T cells." (PMID 34867982, 2021). "Therefore, MST1 deficiency causes T and B cell lymphopenia in human patients, resulting in combined immunodeficiency." (PMID 31052239, 2019). "MST1-deficient patients show susceptibility to bacterial and viral infections, clinical signs of T and B cell lymphopenia, and in addition, although counterintuitive, autoimmune manifestations (this seemingly contradictory outcome of MST1 deficiency is discussed in Section 2.4)." (PMID 31052239, 2019). "In addition to its role in thymic egress, MST1 functions in naive T cell survival and maintenance, may also account for T cell lymphopenia observed in human patients with MST1 deficiency." (PMID 31052239, 2019). "All patients with MST1 deficiency have a similar immunological phenotype, characterized by naive CD4+ and CD8+ T-cell lymphopenia in particular." (PMID 22952854, 2012). "MST1 deficiency was suggested to cause progressive lymphopenia due to the anti-apoptotic role of the enzyme, but the reduced adhesive and chemotactic potential found in murine Mst1−/− lymphocytes was not fully explored in their human equivalents." (PMID 26801501, 2016). "The EAE-resistant phenotype of Mst1−/− mice may potentially be attributed to the lymphopenia and/or alterations in other immune cell types involved in EAE progression." (PMID 24852423, 2014). "Recently, patients bearing LOF mutations of Mst1 are reported with a primary immunodeficiency syndrome characterized by naïve CD4+and CD8+ T-cell lymphopenia in particular, as well as neutropenia, closely assembling with the major defect of Mst1 deficient mice in lymphocyte homeostasis." (PMID 23985272, 2013). "Thus, when patients exhibit marked CD4 lymphopenia and susceptibility to infections in the absence of a bleeding disorder, MST1 deficiency should be considered along with DOCK8 deficiency." (PMID 26801501, 2016). "Disseminated warts have also been frequently found in several autosomal recessive genetic defects that present with CD4 lymphopenia (e.g., RAG1, RHOH, MST1, CORO1A, DOCK8)." (PMID 31781092, 2019). "First, Mst1-KO mice have severe T cell lymphopenia in peripheral lymphoid organs (data not shown), which is consistent with the previous reports." (PMID 31572367, 2019). "Lymphopenia has been observed in the absence of Mst1, but although marginal zone B cell numbers have been shown to reduce in the absence of this kinase, reported reductions in follicular B cells were relatively modest." (PMID 30386341, 2018). "The absence of Mst1 and Mst2 has been shown to induce severe lymphopenia and disruption of Mst1 results in a cell-intrinsic defect of thymic egress of T cells presumably because of a defective response to chemokines." (PMID 30386341, 2018).
colorectal cancer (13 papers, 2016 to 2024). A primary or metastatic malignant neoplasm that affects the colon or rectum. "Decreased MST1/2 expression in colorectal cancer is associated with LN metastasis, vascular invasion, and poor prognosis." (PMID 36552980, 2022). "In colorectal cancer, loss of cytoplasmic MST1 has been associated with higher T and/or N stage, higher tumor grade and poor prognosis." (PMID 32218280, 2020). "A study on more than 1000 colorectal cancer samples showed that loss of cytoplasmic MST1 was an independent adverse prognostic factor in this disease." (PMID 27555231, 2016). "The Hippo pathway is widely dysregulated, especially by MST1, in multiple cancers, including glioma, colorectal cancer, and endometrial cancer, demonstrating that inactivation of MST1 inhibited cancer cell growth and apoptosis." (PMID 36263059, 2022). "According to the results, the expression levels of MST1 in the healthy control sera were higher than those in the colorectal cancer sera." (PMID 29079854, 2017). "Besides NAFLD, MST1/Mst1 also repressed mitophagy during cardiac ischemia-reperfusion injury and colorectal cancer." (PMID 33072754, 2020). "Our results also show MST1 is down-regulated in colorectal cancer of the gastrointestinal tract." (PMID 29079854, 2017). "The sensitivity and specificity of MST1 combined with carcinoembryonic antigen (CEA) and faecal occult blood test (FOBT) in diagnosis of colorectal cancer were 92.3% and 100%, respectively." (PMID 29079854, 2017). "The diagnosis of MST1 Combined with CEA and FOBT in colorectal cancer was analysed by logistic regression and ROC curve." (PMID 29079854, 2017). "And the sensitivity and specificity of MST1 combined with CEA and FOBT in diagnosis of colorectal cancer were 92.3% and 100%, respectively." (PMID 29079854, 2017).
glioma (13 papers, 2016 to 2025). A benign or malignant brain and spinal cord tumor that arises from glial cells (astrocytes, oligodendrocytes, ependymal cells). "Mechanistic investigations further revealed that CUL7 enhances glioma cell growth through MST1 ubiquitination and NF-κB pathway activation." (PMID 40260289, 2025). "Conversely, MST1 overexpression inhibited glioma cell proliferation by modulating the AKT/mTOR pathway." (PMID 37251938, 2023). "There is evidence that SIRT6 is regulated by MST1 and miR-33a and can inhibit the activity of glioma cells." (PMID 36568393, 2022). "CUL7 facilitated the proliferation, invasion and migration of glioma cells by influencing MST1 ubiquitination and activation of NF-κB pathways." (PMID 32252802, 2020). "For example, Mst1 gene silencing induces proliferation of glioma cells, whereas in mouse intestinal epithelium ablation of both Mst1 and Mst2 resulted in cell expansion and proliferation." (PMID 28257933, 2017). "Glioma research indicates that it reduces YAP activity by activating MST1, inhibiting tumor growth." (PMID 40149733, 2025). "Mammalian sterile 20-like 1 (MST1) functions as a suppressor in glioma." (PMID 32252802, 2020). "Interestingly, the results demonstrated that MST1 protein levels were downregulated in high-grade glioma tissues." (PMID 32252802, 2020). "Additionally, work has suggested that homozygous deletion of the p16/MST-1/CDKN2 tumour suppressor gene is less common in Japanese patients with glioma than among Caucasian patients." (PMID 27135830, 2016). "MST1 downregulation in glioma could also be induced through TGF-β signaling." (PMID 33477668, 2021). "In addition, we detected MST1 protein levels in glioma tissues of different grades by IHC." (PMID 32252802, 2020). "Functional MST1 overexpression has been marked by the induction of SIRT6 (Sirtuin 6), reducing glioma cell viability and colony formation and promoting apoptosis through the activation of FOXO3a transcription factor." (PMID 33477668, 2021). "Expression of MST1 and CD44 were negatively correlated, which demonstrated that MST1 protein levels were downregulated in mesenchymal subtype glioma tissues." (PMID 32252802, 2020). "We pretreated glioma cells with XMU-MP-1, an MST1/2 inhibitor." (PMID 36358761, 2022). "Similarly, another study found MST1 binds to AKT and attenuated the AKT and mTOR activity in glioma cell." (PMID 29896440, 2018).